IGF1R (insulin like growth factor 1 receptor)
Diseases named in the same sentence as IGF1R in open-access papers (continued):
Sharing a sentence is not in itself a finding about the gene and the disease.
endometrial cancer (38 papers, 2011 to 2025). Primary or metastatic malignant neoplasm involving the endometrium (mucous membrane that lines the endometrial cavity). "Stigmasterol showed an inhibitory effect by causing cell cycle arrest (G1) in endometrial cancer via suppressing IGF1R/mTOR/Akt pathway." (PMID 40294146, 2025). "It has been reported that after adjusting for BMI, age and histological type, the high expression of IR/IGF-1R is closely related to prognostic high-risk factors, such as the progression of endometrial cancer and lymph node infiltration." (PMID 31440472, 2019). "Why coffee consumption was associated with lower tumor-specific IGF1R levels only among the normal-weight patients stands in contrast to the results found in endometrial cancer patients, where coffee was beneficial in the heavier patients." (PMID 29928262, 2018). "IGF1R has been shown to be strongly expressed in endometrial carcinoma tissue and is inversely correlated with miR-381 levels." (PMID 39001478, 2024). "ALKBH5 enhances the mRNA stability of IGF1R by demethylating its transcripts in the same way, promoting the translation of IGF1R, activating the IGF1R signaling pathway, and increasing the proliferation and invasive ability of endometrial cancer cells." (PMID 37007161, 2023). "Studies of miR-424, a micro RNA that targets and suppresses IGF-1R, show that it is decreased in endometrial cancer cells." (PMID 36052252, 2022). "MiR-320a exerts antitumor effects on endometrial cancer by regulating IGF-1R, which can be used as a target for endometrial cancer gene therapy." (PMID 35719192, 2022). "Since AKT and ERK1/2 play important roles in IGF1R signaling, the apoptotic and anti-proliferative action of methyl jasmonate in endometrial cancer cells can be enhanced by co-targeting the insulin-like growth factor-1 receptor (IGF1R) signaling pathway." (PMID 35264951, 2022). "Several studies have revealed that an overexpression of receptor tyrosine kinase (IGF1R) which mediates actions of insulin-like growth factor 1 (IGF1) is related to endometrial cancer." (PMID 35264951, 2022). "In endometrial hyperplasia and endometrial cancer, the expression of insulin receptors A and B (IR-A and IR-B) and type-1 insulin like growth factor receptor (IGF-1R) is upregulated compared to normal endometrium." (PMID 36052252, 2022). "Of interest, OR5H2 knockdown in both endometrial cancer cell lines led to marked reductions in IGF1R protein levels and in the total and phosphorylated levels of the AKT and ERK1/2 cytoplasmic mediators." (PMID 34204736, 2021). "ALKBH5 knockdown decreased the expression of key molecular IGF1R and inhibited the activation of insulin-like growth factor signaling pathway and inhibited proliferation and invasion of endometrial cancer in vitro." (PMID 32913456, 2020). "IGF1R showed decreased enrichment in the m6A antibody-bound fraction of the endometrial cancer when compared with adjacent normal endometrium, thus indicating that m6A sites on IGF1R mRNAs disappeared in the endometrial cancer." (PMID 32913456, 2020). "Knockdown of IGF-1R reduces the tumorigenic ability of endometrial carcinoma cells, and upregulation of IGF-1R counteracts the inhibitory effects of miR-381." (PMID 33324542, 2020). "IGF-1R is involved in the AKT and ERK signaling pathways, suggesting that miR-381 suppresses tumor growth in endometrial carcinoma by directly targeting IGF-1R to modulate the AKT and ERK pathways." (PMID 33324542, 2020). "Recent studies demonstrated that MK-0646 had a potent anti-proliferative effect in Type I and II endometrial cancer cell lines, associated with a decrease in IGF1-induced IGF1R, AKT, and ERK1/2 phosphorylation." (PMID 29922232, 2018).
endometrial cancer (continued). "In in vitro studies, different IGF-1R inhibiting substances have led to additive and synergistic effects when combined with cisplatin, e.g. the IGF-1R antibodies MK-0646 in endometrial carcinoma and R1507 in small cell lung cancer." (PMID 28591197, 2017). "Two genes (CDC25A and IGF1R) were up-regulated (p = 0.04) in endometrial carcinoma, and CPEB1 was down-regulated (p = 0.05)." (PMID 27271671, 2016). "In conclusion, this study supported the results of animal studies and subclinical studies, demonstrating the feasibility of metformin combined with IGF-1R axis inhibitors in the treatment of endometrial cancer." (PMID 25289085, 2014). "Given that IGF1 ligand downregulation is usually correlated with IGF1R up-regulation, above studies are consistent with constitutive activation of the IGF1R signaling cascade in endometrial cancer." (PMID 24904527, 2014). "Studies by several groups have shown that IGF1 has a significant role in both Type I and II endometrial cancers, emphasizing the importance of altered IGF1R gene expression in the development of a malignant phenotype." (PMID 24904527, 2014). "Cell proliferation was assessed following exposure of Ishikawa and HEC-1B endometrial cancer cell lines to metformin and/or the IGF-1R inhibitor, PPP." (PMID 25289085, 2014). "Data from these assays performed on a panel of endometrial cancers from AA and CA confirmed the array findings for IGF1R, MUC20, and RRAD, but interestingly, qRT-PCR utilizing primers targeted to PSPH did not." (PMID 22783543, 2012). "MiR-625 expression was significantly lower in endometrial cancer tissues than in matching normal samples, and circ_002577 enhanced endometrial cancer development by functioning as a sponge for miR-625, elevating IGF1R expression, and activating the PI3K/Akt pathway." (PMID 35992812, 2022). "Downregulation of IGF-1R expression inhibits the growth of endometrial carcinoma in vitro." (PMID 36230654, 2022). "To investigate whether the expression of IGF1R protein in endometrial cancer adjacent and endometrial cancer were consistent with the ALKBH5, we found that IGF1R were indeed upregulated in endometrial cancer." (PMID 32913456, 2020). "Thus, we demonstrated that ALKBH5 promoted proliferation and invasion of endometrial cancer via erasing IGF1R m6A-modifications, which suggests a potential therapeutic target for endometrial cancer." (PMID 32913456, 2020). "IGF1R expression is significantly higher in endometrial carcinoma than in normal endometrium." (PMID 31320996, 2019). "Interestingly, a different response to IGF1R blocking with MK-0646 was observed in Type I and Type II endometrial cancer." (PMID 29922232, 2018). "Moreover, a human monoclonal IGF1R antibody inhibited endometrial cancer proliferation in clinical trials." (PMID 29922232, 2018). "Most tumors, including endometrial cancers, express high levels of IGF1R." (PMID 29615978, 2018). "Elevated IGF1R mRNA expression was observed in 91.3% of endometrial cancers." (PMID 24904527, 2014). "Hence, these studies suggest that over-expression of the IGF1R and IGF2 genes is associated with poor outcome in endometrial cancer." (PMID 24904527, 2014). "Additionally to the established role of estrogen and progesterone in hyperplasia induction and endometrial cancer onset, are other factors also involved in the development of this cancer, which include IGF-1R, β-catenin and PAX-2." (PMID 24308813, 2013).
endometrial cancer (continued). "IGF-1R is also known to form a hybrid receptor, IR-A/IGF-1R, with the insulin receptor, and this hybrid receptor has been shown to activate the EMT in endometrial cancer." (PMID 36052252, 2022). "Increased insulin and IGF-1 can stimulate the proliferation of endometrial cancer cells by binding to IR and IGF-1 receptors (IGF-1R) and activating downstream signaling pathways." (PMID 31440472, 2019). "Targeting IGF1R with specific monoclonal antibodies inhibited IGF-induced proliferation in both Type I and II endometrial cancer." (PMID 29922232, 2018). "IGF1R-targeting with monoclonal antibodies and specific IGF1R TKIs inhibited IGF-induced proliferation in both Type I and II endometrial carcinomas." (PMID 29922232, 2018). "Cixutumumab, a fully human monoclonal antibody against IGF1R, inhibited IGF1-mediated biological actions and cell signaling events in four endometrial carcinoma-derived cell lines." (PMID 29922232, 2018). "Estrogen can activate IGF1R on endometrial cancer cells, thereby enhancing cellular proliferation through PI3K signaling, a link to IGF1R activation." (PMID 25866823, 2015). "The aim of this study was to investigate the regulation of IGF signaling by metformin in endometrial cancer cells, and to determine the effects of metformin combined with IGF-1 receptor (IGF-1R) inhibitor on cell proliferation and apoptosis." (PMID 25289085, 2014). "The correlation between IGF1R and IGF2 expression levels with endometrial cancer stage was investigated in a study that included specimens from 59 endometrial adenocarcinoma cases, 10 endometrial hyperplasia cases, and 7 normal controls." (PMID 24904527, 2014). "The expression of ER, PR, IGF-1R, β-catenin and PAX-2 have been immunohistochemically investigated in 86 type I endometrial cancer specimens." (PMID 24308813, 2013). "In endometrial cancer cell cultures, metformin treatment lowers secretion of insulin-like growth factor (IGF-1), downregulates expression of insulin receptor and IGF-1R, inhibits phosphorylation of IGF-1R, and increases expression of insulin-like growth factor-binding protein 1 (IGFBP-1)." (PMID 30211120, 2018).
bladder cancer (37 papers, 2010 to 2025). "The tumors harboring high-SOX2/high-IGF1R signature are associated with the worst survival outcome in bladder cancer patients." (PMID 32427884, 2020). "The inhibition or loss of expression of IGF1R significantly decreased the viability of RT112 bladder cancer cells (60%)." (PMID 28882129, 2017). "In this case, IGF1R is associated with the semantic type "Gene or Genome," (abbreviated as gngm) and Carcinoma of bladder is associated with the semantic type "Neoplastic Process" (abbreviated as neop)." (PMID 21284871, 2011). "Recent emerging data indicated that bladder cancers harbouring ATM mutations are susceptible to increased sensitivity to 29 drugs including cisplatin, IGF‐1R inhibitor and BMS‐536924." (PMID 36056635, 2022). "As shown in bladder cancer cells, decorin binds with similar affinities both the IGF1R and IGF1 at distinct sites and inhibits IGF1-mediated IGF1R phosphorylation, without affecting IGF1R protein levels." (PMID 33673232, 2021). "Another study revealed that silencing of LINC00958 attenuated bladder cancer progression by repressing miR-378a-3p and elevating IGF1R expression." (PMID 34702201, 2021). "In bladder cancer, only one study has suggested that LINC00958 facilitated the pathological process of bladder cancer by repressing miR-378a-3p and elevating IGF1R expression." (PMID 34702201, 2021). "In summary, SMYD3 plays critical roles in bladder cancer oncogenesis, such as interactions with IGF-1R and AKT/mTOR in a possible feedback pathway, cell cycle and apoptotic regulation, and autophagy activation via BCLAF1 regulation." (PMID 33637115, 2021). "More recent data have demonstrated that DDR1 is upregulated in bladder cancer tissues and cell lines, where it functionally interacts with both the IGF1R and the IR and modulates ligand-evoked bladder cancer cell motility." (PMID 33673232, 2021). "LINC00958 regulates bladder cancer by inhibiting miR-378a-3p and upregulating insulin-like growth factor 1 receptor (IGF1R)." (PMID 34672237, 2021). "On the contrary, decorin enhances IGF1-evoked IRS-1 degradation and inhibits Akt and MAPK activation, thus blunting the ability of the IGF1R to promote ligand-evoked bladder cancer cells migration and invasion." (PMID 33673232, 2021). "To further examine the potential of SOX2, SOX4, and IGF1R signaling in bladder cancer prognosis, we correlated the expression of these molecules with recurrence-free survival in primary bladder tumors." (PMID 32427884, 2020). "Linsitinib, an IGF1R inhibitor, was used to block IGF2/IGF1R signaling-mediated AKT phosphorylation in SOX2-expressing bladder cancer cells." (PMID 32427884, 2020). "We found that ATM mutation resulted in increased bladder cancer sensitivity to 29 drugs, including cisplatin (P < 0.05), BMS-536924, an IGF-1R inhibitor (P < 0.05), motesanib, a VEGFR inhibitor (P < 0.05), and WHI-P97, a JAK inhibitor (P < 0.05)." (PMID 32922441, 2020). "ATM mutations resulted in increased bladder cancer sensitivity to 29 drugs (P < 0.05), including cisplatin and BMS-536924, an IGF-1R inhibitor." (PMID 32922441, 2020). "And, mammalian target of rapamycin (mTOR) gene and insulin-like growth factor 1 receptor (IGF1R) are direct target of miRNA-100 in bladder cancer, acute myelocytic leukemia, endometrioid endometrial carcinoma and so on." (PMID 28977982, 2017). "Since our evidence suggests that SOX2 activates AKT survival signaling and promotes spheroid-forming ability by inducing IGF2/IGF1R in bladder cancer cells, IGF2 and IGF1R may be potential therapeutic targets for treating bladder cancer." (PMID 32427884, 2020). "The fact that SOX2–IGF2/IGF1R signaling axis confers aggressiveness in bladder cancer suggests that IGF2/IGF1R may serve as therapeutic targets in treating bladder cancer." (PMID 32427884, 2020). "Although IGF2/IGF1R signaling enhances tumor progression in several cancers, it is unclear whether IGF2/IGF1R signaling contributes to bladder cancer progression." (PMID 32427884, 2020).
bladder cancer (continued). "Moreover, we found that SOX2 promotes bladder cancer cell survival by inducing the IGF2/IGF1R pathway, thereby activating AKT survival signaling." (PMID 32427884, 2020). "Third, we propose that ATM-MT bladder cancer patients may benefit from the combined application of ICIs and IGF-1R inhibitors, which opens a new approach for clinical treatment, but further experimental confirmation is still needed." (PMID 32922441, 2020). "Moreover, we observed SOX2 and IGF1R levels are significantly correlated with poor prognosis in bladder cancer patients." (PMID 32427884, 2020). "Pharmacological inhibition of IGF1R or AKT inhibits bladder cancer cell survival." (PMID 32427884, 2020). "Moreover, we observed that IGF1R expression correlates with poor recurrence-free survival in bladder cancer patients." (PMID 32427884, 2020). "To understand whether IGF2/IGF1R signaling is responsible for high-SOX2 expressing bladder cancer cell growth, we knocked down IGF2 and IGF1R." (PMID 32427884, 2020). "Furthermore, we identified IGF2 and IGF1R as AKT upstream molecules which induce AKT phosphorylation in SOX2-positive bladder cancer cells." (PMID 32427884, 2020). "Our present results confirmed that SOX2 regulates IGF2/IGF1R signaling in bladder cancer cells." (PMID 32427884, 2020). "Knockdown of IGF2 and IGF1R attenuated the growth of bladder cancer cells." (PMID 32427884, 2020). "Previous studies focused on the role of IGF1R in bladder cancer invasiveness." (PMID 28882129, 2017). "Moreover, knocking down IGF2 and IGF1R diminished bladder cancer cell growth." (PMID 32427884, 2020). "Furthermore, IGF1R was involved in bladder cancer cell motility and invasion in the presence of an exogenous ligand suggesting that the IGF1R might play a critical role in the establishment of the invasive phenotype in urothelial neoplasia." (PMID 28882129, 2017). "For further validation, Kaplan–Meier survival plots with GHR, GH1, IGF-1 receptor (IGF1R), or IGF1 as the reference gene were generated from TCGA database, including 405 patients with bladder cancer." (PMID 40806252, 2025). "For example, the expression of stem cell markers such as SOX2, IGF1R, SOX4, ALDH1, and CD44 affects the likelihood of recurrence and metastasis in bladder cancer." (PMID 41153362, 2025). "In bladder cancer, METTL3 upregulates PCAT6 expression and increases IGF1R RNA stability by forming the PCAT6/IGF2BP2/IGF1R complex, which activates the NF-KB and PI3K/AKT signaling pathways." (PMID 37996892, 2023). "Lastly, pharmacological inhibition of IGF1R, using linsitinib, also inhibited the SOX2-mediated spheroid formation of bladder cancer cells under low-serum stress." (PMID 32427884, 2020). "All these data verify SOX2 promotes bladder cancer cell growth and survival by inducing IGF2/IGF1R signaling." (PMID 32427884, 2020). "The PCR signals of six genes (KLK3, TMPRSS2, KLK4, IGF1R, VEGF, and MYC) were successfully amplified in bladder cancer cell lines." (PMID 32781788, 2020). "This suggests that IGF2 and IGF1R are crucial for SOX2-mediated growth and survival of bladder cancer cells." (PMID 32427884, 2020). "In our preliminary studies on J82 bladder cancer, GHRH agonist MR-409 downregulated the expression of IGF1-R, inhibited the phosphorylation of IGF1-R and its downstream AKT and ERK pathways." (PMID 29983893, 2018). "They found that overexpression of miR-145 led to inhibition of IGF-1-induced cell proliferation and miR-145 was shown to directly bind to 3′UTR of IGF-1R and IRS-1 in the bladder cancer cells." (PMID 25628647, 2014). "Finally, by analyzing the GDSC database, we found that ATM mutations resulted in increased bladder cancer sensitivity to 29 drugs, including cisplatin, the first-line treatment for bladder cancer, and BMS-536924, an IGF-1R inhibitor." (PMID 32922441, 2020).
bladder cancer (continued). "Indeed, we found that pharmacological inhibition of IGF2/IGF1R signaling with linsitinib decreased AKT phosphorylation and attenuated bladder cancer cells’ SOX2-mediated colony-forming ability." (PMID 32427884, 2020). "Hence, our findings that SOX2 activates IGF2/IGF1R signaling and predicts poor prognosis further link IGF2/IGF1R signaling to SOX2 mediated aggressiveness in bladder cancer." (PMID 32427884, 2020). "Interestingly, decorin inhibits IGF1-mediated phosphorylation of IGF1R, without affecting the IGF1R protein levels, thereby blocking the migratory and invasive capabilities of bladder cancer cells." (PMID 38892104, 2024). ""The IGF1R is up-regulated in bladder cancer compared with non-malignant bladder, and might contribute to a propensity for invasion"." (PMID 21284871, 2011).